RN7SL491P (RNA, 7SL, cytoplasmic 491, pseudogene)
Gene: Miscellaneous RNA gene on chromosome 19 (35,414,881 to 35,415,149, reverse strand). Ensembl gene ENSG00000264400.
Homologues: Orthologues: chimpanzee Metazoa_SRP (98% identical). Paralogues in human: Metazoa_SRP (80% identical), RN7SL96P (79% identical), Metazoa_SRP (78% identical), RN7SL371P (78% identical), RN7SL123P (78% identical), RN7SL134P (78% identical), RN7SL391P (78% identical), RN7SL774P (78% identical), RN7SL811P (78% identical), RN7SL274P (77% identical), RN7SL596P (77% identical), Metazoa_SRP (77% identical), and 708 more.